IGF1R (insulin like growth factor 1 receptor)
Diseases named in the same sentence as IGF1R in open-access papers (continued):
Sharing a sentence is not in itself a finding about the gene and the disease.
cancer (continued). "This has made IGF-1R a prominent target molecule for pharmacological companies to develop new anti-cancer agents." (PMID 27275536, 2016). "The type I insulin-like growth factor receptor (IGF1R) is a tyrosine kinase receptor involved in cancer progression and metastasis formation and its over-expression and activation has been reported in many cancer types, especially in breast cancer." (PMID 27145373, 2016). "OSI-906 (linsitinib) is a selective dual inhibitor of the IR and IGF-1R and therefore a promising candidate for the treatment of various cancer types." (PMID 27849005, 2016). "Overall, selection of suitable epitopes of the IGF-1R as antigens, and utilizing them for raising MAbs against the IGF-1R, with ability of cancer inhibition would be beneficial in cancer treatment." (PMID 28261624, 2016). "The ability of unrelated disrupted gene products to control IGF1R transcription emphasizes the central role of this tyrosine kinase receptor as a critical regulator of cancer initiation and progression." (PMID 27285981, 2016). "Like EGFR, IGF-1R also plays a role in the maintenance of the oncogenic phenotype in various cancers and is known to mediate anti-apoptotic signals and cell proliferation." (PMID 27716204, 2016). "The IGF1R promotes cancer cell proliferation and survival and, on the other hand, prevents apoptosis." (PMID 27179633, 2016). "The insulin-like growth factor-1 receptor (IGF-1R) overexpression contributes to the development of a variety of cancers." (PMID 27813495, 2016). "Targeting IGF-1R in human cancers seemed to be a promising approach, but the results of the clinical trials with IGF-1R inhibitors as a single agent proved to be disappointing." (PMID 27849005, 2016). "The immense expression of IGF-1R in cancer cells or tissues combined with its important role in cancer cell growth makes it a striking target to combat malignant diseases." (PMID 27051190, 2016). "IGF-1 is a mitogen, which is usually overexpressed in cancer cells maintaining cell cycle program regulated by the IGF-1R and help in transformation and protection of cancer from apoptosis." (PMID 27806706, 2016). "It is well known that rapamycin mediates AKT activation through an IGF-1R-dependent mechanism, which is related to rapamycin resistance in cancer." (PMID 27274989, 2016). "Furin processes a variety of substrates, e.g. IGF1R, that support cancer cell viability and proliferation." (PMID 27572312, 2016). "The IGF-1R/AKT/mTORC1 pathway is aberrantly activated in multiple cancers and there is abundant literature that this pathway contributes to apoptosis resistance and survival." (PMID 27050276, 2016). "The effects of CAFs, IGF1, and IGF1R inhibitors on the motility of cancer cells were examined by wound-healing assay or invasion assay under normoxia (20% O2) and hypoxia (1% O2)." (PMID 27487118, 2016). "The IGF1R is highly expressed in most types of cancer and is regarded as a promising therapeutic target in oncology." (PMID 27446805, 2016). "Like EGFR, IGF-1R is involved in normal cellular growth as well as transformation and progression of malignancy in various cancers." (PMID 27716204, 2016). "Deregulated IGF-1R-AKT signaling influences multiple nodes of cancer cell physiology and assists in migration, metastasis and acquirement of radio/chemoresistance." (PMID 27819360, 2016). "Insulin-like growth factor 1 receptor (IGF1R) is a prevalent signaling pathway in human cancer that supports cell growth/survival and thus contributes to aggressive biological behavior." (PMID 27532210, 2016). "The IGF-1R and cancer link formed a few decades ago from sequence homology identification and in vitro validation is reinforced once again by epidemiological studies, which are now coming of age." (PMID 25964779, 2015).
cancer (continued). "The IGF-1R pathway plays a critical role in tumorigenesis, angiogenesis, metastasis, and resistance to existing forms of anti-cancer therapy." (PMID 25944691, 2015). "Most human cancers overexpress both the IGF-1 receptor (IGF-1R) and insulin receptor (IR) isoforms, leading to the formation of hybrid IGF-1R/IRs." (PMID 25874233, 2015). "Increased IGF-1R levels have been detected in many cases of breast malignancy, most often independently of cancer subtype, ER, PR or HER2 status." (PMID 25743390, 2015). "The insulin-like growth factor type 1 receptor (IGF-1R) plays a key role in the development and maintenance of cancer." (PMID 25964779, 2015). "Overall, although the precise mechanisms of metformin’s anti-cancer effects were elusive, our data suggested that it acts partially through inhibiting IGF-1R signaling pathway." (PMID 26287334, 2015). "Genetic alterations of IGF-1R leading to varying levels of their expression are found to have a link in cancer." (PMID 25866791, 2015). "In particular, germline polymorphisms in IGF1, IGF1R, and IGFBP3 are associated with increased risk of breast, prostate, lung, and pancreatic cancers." (PMID 25964777, 2015). "Due to the important role of IGF-1R in proliferation and survival, inhibition of IGF-1R has been shown to be an efficient approach for cancer therapy." (PMID 26307972, 2015). "Dynamic cooperative signaling interactions between the IGF-1R and integrins are necessary for the growth and migration of normal cells and also for invasiveness and metastasis of cancer cells." (PMID 26191041, 2015). "When compared with the control cells as well, the indicated cixutumumab-treated or IGF-1R-silenced cancer cells showed increased levels of STAT3 phosphorylation, which was established by western blotting." (PMID 26465273, 2015). "Early clinical trials of IGF-1R inhibitors showed potentially promising results in these rare cancers, but unfortunately, the IGF-1R and insulin receptor inhibitor linsitinib showed limited therapeutic benefit in a recent phase III trial." (PMID 26793165, 2015). "Because metformin has both hypo-glycemic and anti-cancer effects, it becomes a promising candidate in combination with anti-IGF-1R mAbs to target SCLC." (PMID 26287334, 2015). "Interaction between the epidermal growth factor receptor (EGFR) and the insulin-like growth factor receptor (IGF-1R) has been well established in many cancer types." (PMID 25355701, 2015). "We also observed transcriptional upregulation of IGF2 in cancer cells after IGF-1R blockade by monoclonal antibody." (PMID 26465273, 2015). "Combating resistance is one of the main challenges in the currently available IGF-1R inhibitor-based cancer therapies." (PMID 26515601, 2015). "Previous studies have shown that FAK regulates IGF1R stability and auto-phosphorylation in several human cancer cells." (PMID 25749031, 2015). "Accordingly, a variety of strategies to target IGF-1R have been in preclinical or clinical stages for the treatment of cancer patients." (PMID 25944691, 2015). "Studies in cultured cells have demonstrated that the IGF-1R is frequently overexpressed in cancer cell lines." (PMID 25866791, 2015). "The insulin-like growth factors (IGFs), IGF-1 and IGF-2, are ligands that bind to IGF receptor (IGF-1R,) and regulate cancer cell proliferation, survival, and metastasis." (PMID 25866791, 2015). "IGF-1R is now considered to be an attractive target for cancer treatment and there are some ongoing clinical trials testing the IGF-1R-targeted drugs." (PMID 26287334, 2015). "mTOR is an intracellular protein, playing a major role in protein synthesis and influencing the cell growth, differentiation and apoptosis: this pathway is unregulated in many cancers, leading to the permanent activation, often under the influence of IGF1R." (PMID 26541413, 2015).
cancer (continued). "Epidemiological studies indicate a strong association between expression levels of both IGF1 and its receptor (IGF1R) and cancer initiation/progression." (PMID 25848982, 2015). "There is a wealth of evidence that implicates the insulin-like growth factor-1 receptor (IGF-1R) as a major target in cancer drug discovery and its role in the development of resistance to targeted therapies." (PMID 26350593, 2015). "The first recruited mAb against IGF-1R is CP-751,871 (figitumumab) which has demostrated good pre-clinical antitumor efficacy against several cancers including BrCa." (PMID 25743390, 2015). "It has been shown that PPARα reduced cellular functions by attenuating IGF-1R and Akt activity in diverse cancer cells." (PMID 25695641, 2015). "First, they directly and specifically kill IGF1R+ cancer cells even at a low level of surface expression as CD8+ CTLs are capable of responding to a single antigen molecule." (PMID 26173023, 2015). "The early evidence linking the IGF1R to cancer was the finding that the transformation of mouse embryo fibroblasts (MEFs) by many, but not all, tested oncogenes requires an intact Igf1r gene." (PMID 25699021, 2015). "miR-122 suppresses IGF-1R expression and attenuates IGF-1R/Akt signaling, which sustains the activity of glycogen synthase kinase 3 beta and in turn represses cancer cell proliferation." (PMID 26302777, 2015). "In conclusion, our data identify anti-IGF-1R monoclonal antibody-induced cancer–stromal cell communication via STAT3-dependent IGF-2 production in cancer cells and a positive IGF-2/CXCL8 feedback loop through the intercellular IGF-2/IGF-2R system." (PMID 26465273, 2015). "In the prostate, IGF-1R plays a critical role in normal gland growth and development, as well as in cancer initiation and progression." (PMID 25906745, 2015). "Novel aspects of IGF1R/IR in cancer, such as biased agonism, integrin β3 signaling, AHR, and new therapeutic targeting strategies will be discussed." (PMID 25699021, 2015). "IR isoform (IR-A) is overexpressed in cancer and it is the fetal isoform of IR (while other half is IR-B involved in regulating glucose uptake) and IGF-1R is also overexpressed in cancer." (PMID 25866791, 2015). "IGF-1R has recently been proposed as a novel target for cancer treatment because it is overexpressed in a range of cancers." (PMID 26302777, 2015). "Only then can we pinpoint the cancer subtypes that will benefit from IGF1R therapeutics, alone or in combination with other inhibitors." (PMID 25964777, 2015). "IGF-1R signaling in cancer cells results from up-regulation of the receptor or its ligands (IGF-I and IGF-II) and contributes to the emergence of chemotherapeutic resistance." (PMID 26029660, 2015). "Previous reports have shown that PPARα promotes apoptosis and inhibits cellular functions by IGF-1R signalling and Akt phosphorylation in various cancer cells." (PMID 25695641, 2015). "Alternations and co-expression of IGF-1R and adhesion signaling components have been reported in several different cancers." (PMID 26191041, 2015). "The IGF-1R trials included not only a wide range of cancer types, but also a broad range of molecular determinants and pre-trial treatment regimens." (PMID 25964779, 2015). "Co-immunoprecipitation and degradation studies demonstrated that FAK directly binds to, stabilizes, and activates IGF1R in human cancer cells." (PMID 25749031, 2015). "It is likely that distinct adhesion complex proteins modulate IGF-1R signaling during cancer progression or adaptive responses to therapy." (PMID 26191041, 2015). "As antisense strategies do not work in humans, several approaches were undertaken in the late 1990s to target the IGF-1R in anti-cancer therapeutics, and with strong pre-clinical evidence multiple trials commenced." (PMID 25964779, 2015). "Expression and activation of the insulin-like growth factor-1 receptor (IGF-1R) is commonly detected in various human cancers." (PMID 24704793, 2014).
cancer (continued). "The IGF-1 receptor (IGF-1R) has a dominant role in cancer cell survival via autocrine and paracrine mechanisms to promote oncogenesis." (PMID 24970012, 2014). "Numerous phase I and phase II studies for pediatric cancers are currently underway with either IGF-1R inhibitors alone or combination regimen, however, the clinical efficacy is still unsatisfactory." (PMID 25362349, 2014). "The expression pattern of the cancer progenitor/stem cell-like marker panel (CD24low/CD44high/CD49bhigh) remained unchanged in PCa cells overexpressing IGF1R or INSRs." (PMID 24809298, 2014). "Collectively, these data indicated that PTB-U-box led to an inhibition of cancer cell invasion via down-regulating IGF-1R and IR." (PMID 24970814, 2014). "Currently more than 100 clinical trials are evaluating the effect of IGF1R targeting therapeutics as single agents or in combination with standard treatments in several cancer entities." (PMID 24809298, 2014). "IGF1R is expressed in many types of cancer cells, including NSCLC, and enhanced activation of IGF1R is implicated in resistance to chemotherapy and targeted therapies such as EGFR-TKIs." (PMID 24489728, 2014). "IGF-1R is highly expressed in epithelial differentiated NSCLC tumors, and therefore, blocking IGF-1R signaling inhibits the proliferation and survival of cancer cells." (PMID 24816813, 2014). "Consistent with a previous report, we found that inhibition of IGF1R signaling alone almost completely restored the sensitivity of HER2-positive cancer cells to trastuzumab in vitro." (PMID 24571711, 2014). "Insulin growth factor 1 receptor-mediated pro-oncogenic signaling has been demonstrated in multiple cancers and molecular mechanisms leading to dysregulation of IGF-1R has been an intense focus of cancer research." (PMID 25628647, 2014). "IGF-1R is a potential target for cancer therapeutics since it plays a fundamental role in the progression of several types of cancer, and is involved in resistance to cancer therapy." (PMID 24709958, 2014). "IGF-1R is a tyrosine kinase receptor, which involves in the regulation of proliferation, apoptosis, differentiation and malignant transformation of cancer cells." (PMID 24667580, 2014). "We found that miR-133a can suppress cancer cell invasion, metastasis and proliferation abilities, and we also found that inhibition of IGF-1R and TGFBR1 reduces both cell invasion and cell proliferation." (PMID 24816813, 2014). "Confirming this critical role, in preclinical settings, a large amount of experimental data clearly demonstrates that inhibition of IGF-1R would be beneficial for cancer treatment." (PMID 24276851, 2014). "We have provided evidences that such an engineered molecule, PTB-U-box, can effectively degrades IGF-1R/IR, inhibits cell proliferation and invasion, increases chemo-sensitivity and reduces glucose metabolism when ectopically expressed in cancer cells." (PMID 24970814, 2014). "Further work is required (i) to determine the possible role of IGF-1R signalling in VGSC expression/activity in cancer cells, and (ii) to elucidate the possible overlap between the IGF-1R and InsR signalling in this." (PMID 24493753, 2014). "Activation of IGF1R which is essential for the initiation and progression of many cancers starts by ligand-initiated kinase activation with IGF1 or IGF2." (PMID 25344917, 2014). "IGF1R is found overexpressed in many types of cancer cells and is upregulated in primary human HCCs." (PMID 24813441, 2014). "Low levels of IGF-1R mRNA were already reported in certain types of cancer, for example breast cancer." (PMID 25333772, 2014). "The IGF1R pathway is important in promoting oncogenic transformation, growth, and survival of cancer cells, and IGF1R overexpression has been demonstrated in many cancers." (PMID 25110710, 2014). "In recent years, the IGF1R has emerged as a promising therapeutic target in cancers, including prostate tumors." (PMID 24434591, 2014).
cancer (continued). "IGF-1R/AKT pathway has been identified to involve in the regulation of multiple biological processes of cancers." (PMID 24667580, 2014). "Signaling through IGF1R promotes cell proliferation, apoptosis, and invasion of cancer cells; which are all integral steps in cancer metastasis." (PMID 25566502, 2014). "Our study hereby provides another alternative strategy -- targeted degradation of IGF-1R and IR simultaneously -- for the treatment of cancers with IGF-1R/IR co-expression and over-activation." (PMID 24970814, 2014). "Consistent with the key role of the IGF system in cancer progression, IGF1R and IGF2 levels were much higher in advanced stage (Stages III–IV) malignant tissue compared to early stages or endometrial hyperplasia." (PMID 24904527, 2014). "For the past two decades, IGF-1R inhibitors have been developed for anticancer therapies in a variety of pediatric and adult cancers." (PMID 25362349, 2014). "IGF1R and INSRA overexpression increased the migration and invasion potential of all the tested cancer cell lines, while IGF1R and INSR downregulation reduced cell migration and invasion." (PMID 24809298, 2014). "Among RTKs, the insulin-like growth factor type-1 receptor (IGF-1R) is one of the most important players in cancer development." (PMID 24276851, 2014). "Numerous clinical cancer trials have been performed that target IGF1R, including those with drugs that inhibit the IGFIR tyrosine kinase using monoclonal antibodies and small molecules." (PMID 25092925, 2014). "Unlike INSR expression, which contributes less to tumorigenesis, the malignancy of dysregulated IGF-1R in cancer progression has been investigated, and targeting IGF-1R in cancer treatment is currently under development." (PMID 24816813, 2014). "This study illustrates a mechanism by which cancer progresses and reinforces the suitability of IGF1R as a therapeutic potential in HCC." (PMID 24813441, 2014). "The IGF1R is overexpressed in several cancers, including in OSCC tissues and cell lines, and essential for malignant transformation and progression." (PMID 24410957, 2014). "Increased expression of IGF-1R has been reported in many carcinomas including breast, prostate, pancreas and colon, and thus the blockade of IGF-1R activity can significantly induce growth inhibition and apoptosis in these cancer cells." (PMID 24618835, 2014). "Several neutralizing antibodies or small molecule receptor kinase inhibitors have been developed for targeting the IGF1 receptors (IGF1R) and are tested in clinical studies in various cancer entities." (PMID 24809298, 2014). "Extensive in vitro and in vivo studies have implicated IGF-1R, IGF-1, and IGF-2 signaling in cancer development, progression, and maintenance." (PMID 25424625, 2014). "Similarly, we observed that MK-2206 treatment in the IGF1R-dependent GEO cells reduced cell proliferation and increased cell death in a concentration dependent manner while MK-2206 has been shown to be effective in causing cell death in different types of cancer." (PMID 24581231, 2014). "Over-activation of IGF/IGF-1R and insulin/IR signaling pathway has been reported to promote several cancer hallmarks, including uncontrolled cell proliferation, migration, transformation, metastasis, angiogenesis and glycolysis." (PMID 24970814, 2014). "The insulin-like growth factor type 1 receptor (IGF-1R) plays a key role in the development and progression of cancer; however, therapeutics targeting it have had disappointing results in the clinic." (PMID 24276851, 2014). "Reduced expression of IGF-1R and downstream regulatory proteins inhibits the development of cancer, and the results presented here demonstrated that phloroglucinol inhibited cancer by regulating IGF-1R pathways." (PMID 24970012, 2014).